MAD2L1 (mitotic arrest deficient 2 like 1)
Diseases named in the same sentence as MAD2L1 in open-access papers (continued):
Sharing a sentence is not in itself a finding about the gene and the disease.
pulmonary fibrosis (1 paper, 2022). Chronic progressive interstitial lung disorder characterized by the replacement of the lung tissue by connective tissue, leading to progressive dyspnea, respiratory failure, or right heart failure. "In this study, we aimed to uncover the role of MAD2L1 in pulmonary fibrosis to find a novel therapeutic target for IPF treatment." (PMID 36247080, 2022). "Inhibition of MAD2L1 led to mitochondria damage, augmentation of ROS production, and cellular senescence, and induction of extracellular matrix thus promoted pulmonary fibrosis." (PMID 36247080, 2022). "Altogether, MAD2L1 inhibition promotes the establishment of a profibrotic microenvironment, thus inducing pulmonary fibrosis." (PMID 36247080, 2022). "MAD2L1 inhibition can augment mitochondrial dysfunction and thus contribute to the pathogenesis of pulmonary fibrosis." (PMID 36247080, 2022). "The abnormal expression of MAD2L1 in our fibrotic lung meta-dataset drove us to explore the role of MAD2L1 in the progression of pulmonary fibrosis." (PMID 36247080, 2022). "In this study, we demonstrated that MAD2L1 plays a crucial role in the pathogenesis of pulmonary fibrosis." (PMID 36247080, 2022). "Taken together, these results reveal that alleviation of alveolar epithelial cell mitochondrial damage arising from augmentation of MAD2L1 may be a novel therapeutic strategy for mitigating pulmonary fibrosis." (PMID 36247080, 2022). "Therefore, we hypothesized that MAD2L1 inhibition may augment lung fibrosis." (PMID 36247080, 2022). "However, the role of MAD2L1 in pulmonary fibrosis has not been explored." (PMID 36247080, 2022).
soft tissue sarcoma (1 paper, 2021). A malignant neoplasm arising from muscle tissue, adipose tissue, blood vessels, fibrous tissue, or other supportive tissues excluding the bones. "The abnormal expression of MAD2 (also known as MAD2L1) may be related to the pleomorphic morphology and impaired mitoses of soft-tissue sarcoma and the high-grade tumour progression of the TA subgroup." (PMID 34838000, 2021).
squamous cell carcinoma (1 paper, 2020). A carcinoma arising from squamous epithelial cells. "Further, multivariate cox regression analysis showed that patients age, p-stage, M status and NDC80 expression work as independent prognostic indicators in adenocarcinoma, meanwhile, T stage, M status and MAD2L1 expression work as an independent indicators in squamous cell carcinoma." (PMID 32795325, 2020).
viral hepatitis (1 paper, 2009). An acute or chronic inflammation of the liver parenchyma caused by viruses. "The band of MAD2L1 was also detectable in 17/25 patients while in non-viral hepatitis it was not detectable." (PMID 19664251, 2009).
cancer (62 papers, 2008 to 2025). A tumor composed of atypical neoplastic, often pleomorphic cells that invade other tissues. "These genes, including Smc2, Mcm3, Ccnd1, Rasal2, Mcm6, and Mad2l1, are linked to cancer progression and metabolic regulation." (PMID 39272991, 2024). "A variety of highly malignant human cancers express mitotic arrest deficient 2 like 1 (MAD2L1), a transcription factor that plays a critical role in their development and progression." (PMID 36637946, 2023). "The genotypic polymorphisms of MAD1L1 and MAD2L1 genes significantly increased the risk of certain cancers." (PMID 37007941, 2023). "Mutation frequencies of the SAC genes remained low, and only rare polymorphisms in MAD1L1, MAD2L1, and BUB1b were found in certain cancers involved in the modulation of the cell cycle arrest." (PMID 37007941, 2023). "Altogether, we elucidated that MAD2L1 is highly expressed in multiple types of human cancers (including HCC) and is significantly associated with poor prognosis in patients with HCC." (PMID 36637946, 2023). "Dysregulation of MAD2L1 is associated with chromosomal instability and substantial aneuploidy, which frequently occurs in cancer cells." (PMID 33800494, 2021). "In Mad2l1-deficient murine T-ALLs, HCAs and HCCs, the average karyotype of cell populations is shown by aCGH to involve pan-cancer and tissue-specific patterns of whole chromosome loss and gain." (PMID 28318489, 2017). "The rapid growth of Mad2l1-deficient liquid and solid tumors stands in contrast to previous data showing that Mad2l1 is essential for the survival of cancer cell lines and for development of early mouse embryos." (PMID 28318489, 2017). "Dysregulation of MAD2L1 is associated with chromosomal instability and substantial aneuploidy which frequently occur in cancer." (PMID 27835911, 2016). "MAD2L1 dysregulation promotes tumorigenesis by inducing chromosomal instability and aneuploidy, and its overexpression has been linked to enhanced progression in various cancers." (PMID 39857609, 2024). "In all cancer types, increased MAD2L1 expression was associated with poor DFS (RFS) in HCC." (PMID 36637946, 2023). "Mitotic arrest deficient 2 like 1 (MAD2L1) is a component of the mitotic spindle assembly checkpoint that prevents the onset of anaphase until all chromosomes are properly aligned at metaphase and is a potential therapeutic target in cancers." (PMID 36247080, 2022). "Shared genes by all cancers with an adverse prognosis (high positive global meta-z-scores), such as MAD2L1, CCNB1, NUF2 and UBE2C, were associated with gene ontology (GO) enrichment analysis terms related to proliferation, replication and mitosis, similar to adult tumors." (PMID 33670534, 2021). "In conclusion, CDK1 and MAD2L1 were adverse prognostic biomarkers for LUAD whose increased expression could render patients with LUAD a high risk of cancer recurrence and poor survival, suggesting that they might be applied as potential targets for LUAD treatment." (PMID 27835911, 2016). "Among these therapeutic targets, we focused on ANLN (miR-195-5p target) and MAD2L1 (miR-195-3p target) and revealed their cancer-promoting functions in LUAD cells." (PMID 40723231, 2025). "In multiple cancers, overexpression of MAD2L1 is involved in the malignant transformation of cancer cells, and patients overexpressing MAD2L1 have a poor prognosis." (PMID 40723231, 2025). "To investigate the signaling pathways influenced by ANLN and MAD2L1 in cancer, we generated genome-wide gene expression profiles using A549 cells transfected with siANLN or siMAD2L1." (PMID 40723231, 2025). "In conclusion, this study confirms the pivotal role of MAD2L1 in the proliferation and biological characteristics of cancer cells." (PMID 40231267, 2025). "Machine learning analysis pinpointed 14 feature genes, among seven were associated with cancer (NAT1, BIRC3, EZH2, MAD2L1, ATP2A3, HMGA1, and BST2)." (PMID 41255601, 2025).
cancer (continued). "Database searches indicated that NAT1, BIRC3, EZH2, MAD2L1, ATP2A3, HMGA1, and BST2 are cancer-associated genes." (PMID 41255601, 2025). "An immunohistochemical analysis revealed that MAD2L1-positive staining was predominantly observed in the nucleus of the cancer cells in GC tissue." (PMID 38698201, 2024). "Overexpression of mitotic arrest deficiency 2 (MAD2/MAD2L1), a pivotal component of the spindle assembly checkpoint (SAC), resulted in many types of cancer." (PMID 39551802, 2024). "Survival and prognosis analyses for MAD2L1 in these cancer types of interest indicated that HCC patients with high MAD2L1 expression had a poor prognosis." (PMID 36637946, 2023). "The overexpression of MAD2L1 is associated with HCC stage, adjacent organ invasion and poor prognosis and the gene has become a potential biomarker for various cancers." (PMID 38053725, 2023). "It has become increasingly clear that MAD2L1 plays a significant role in human cancers, including HCC, during their initiation and progression." (PMID 36637946, 2023). "Analyses have been performed on the expression and survival of MAD2L1 in a wide range of human cancers." (PMID 36637946, 2023). "We performed a pan-cancer analysis for MAD2L1 prognosis and expression using The Cancer Genome Atlas and Genotype-Tissue Expression data in the present study." (PMID 36637946, 2023). "Based on the mRNA expression levels of MAD2L1, we divided the cancer cases into high- and low-expression groups." (PMID 36637946, 2023). "Changes in MAD1L1 and MAD2L1 levels were detected in many cancer cell lines and tumor biopsy samples." (PMID 37007941, 2023). "The findings demonstrated that the hub genes ORC1, CDC6, CHEK1, and MAD2L1 promoted the cell cycle checkpoint signaling, which is essential in cancer progression." (PMID 37945594, 2023). "In this study, we first conducted a pan-cancer analysis of MAD2L1’s expression using TCGA data, after which the GEPIA database was further employed to validate MAD2L1’s expression." (PMID 36637946, 2023). "The seven DEGs (AURKA, BUB1, CDC6, MAD2L1, NDC80, ZWINT, and TIMELESS) coexpressed only in the LC&OC coexpression network have been associated with the acquisition of the hallmarks of cancer." (PMID 36101460, 2022). "MAD2L1 is a vital component of the spindle assembly checkpoint and tends to be overexpressed in many cancer types." (PMID 35804892, 2022). "MAD2L1 has been reported as a novel oncogene that plays a role in regulating cancer cell growth and apoptosis." (PMID 35783270, 2022). "Overexpressing MAD2L1 has shown the effect on cancer cell proliferation, migration, invasion, and cell cycle arrest." (PMID 34655361, 2021). "Among humans, inhibition of MAD2L1 expression inhibits the proliferation and migration of cancer cells." (PMID 34685648, 2021). "Consistently, miR-139-5p was downregulated in LUAD and exerted the ability to inhibit proliferation, migration, and invasion of cancer cells by targeting MAD2L1." (PMID 34987577, 2021). "Dysregulation of MAD2L1 induces the instability of chromosomes and chromosomal aneuploidy, which are common events in cancer." (PMID 31886163, 2019). "Collectively, the role of MAD2L1 in cancer pathogenesis and the related molecular mechanisms need to be assessed with in-depth studies." (PMID 31886163, 2019). "Down-regulation of MAD2L1 was demonstrated to be involved in suppressing the proliferation, migration, invasion, apoptosis induction and cell cycle arrest of cancer cells (Li, Bai & Zhang, 2017)." (PMID 29785339, 2018). "MAD2B is on chromosome 1p36 and homologous to the spindle checkpoint gene MAD2 (MAD2L1), which plays an important role in aneuploidy, one important character of the majority of human cancers." (PMID 27957796, 2017).
cancer (continued). "We conclude that loss of Mad2l1 in adult tissues can be strongly oncogenic, in contrast to heterozygous Mad2l1 deletion, which is only weakly cancer promoting." (PMID 28318489, 2017). "Germline deletion of murine Mad2l1 is lethal and RNAi-mediated depletion of Mad2l1 in cancer cells results in mitotic catastrophe and cell death within approximately six cell doublings." (PMID 28318489, 2017). "Mad2l1-null cells must therefore proliferate extensively subsequent to a tumor-initiating genetic event (a common characteristic of cancer)." (PMID 28318489, 2017). "MAD2L1 has been found to be overexpressed in several types of tumor or cancer cell lines, including breast, lung, liver and stomach." (PMID 26287798, 2015). "Other genes associated to other cancers (e.g. BUB1 in bladder, MAD2L1 in breast) are involved in spindle checkpoint." (PMID 19753302, 2009). "MAD2L1 serves as a therapeutic target molecule in various cancers, including LUAD." (PMID 40723231, 2025). "Among these, NAT1, BIRC3, EZH2, MAD2L1, ATP2A3, HMGA1, and BST2 are known cancer-associated genes." (PMID 41255601, 2025). "Notably, overexpression of genes involved in the mitotic spindle checkpoint, such as NUF2, MAD2L1, and BUB1, has been linked to chemotherapeutic responses in various cancer types." (PMID 40643514, 2025). "Additionally, univariate Cox regression analyses indicated that high MAD2L1 expression was positively correlated with poorer OS across different types of cancers." (PMID 39387242, 2024). "We used the Genotype-Tissue Expression database to validate MAD2L1 expression in 14 cancer types." (PMID 36637946, 2023). "Changes in MAD1L1 and MAD2L1 may serve as biomarkers for cancer as a potential strategy during anti-cancer treatment." (PMID 37007941, 2023). "MAD2L1, as a novel oncogenic gene, plays a role in regulating cancer cell growth and apoptosis and could be used as a new biomarker for diagnosis and therapy in CRC." (PMID 32153633, 2020). "In conclusion, the present study has shown that CDK1 and MAD2L1 are overexpressed in LUAD tissues and that its up-regulation may be indicative of poor survival rates and a higher risk for cancer recurrence, and it could have a potential role as a prognostic marker in LUAD patients." (PMID 27835911, 2016). "In summary, in the present work, we report that BAG2, MAD2L1, and MDK are bona fide cancer-driver genes for MPM worth of further studies." (PMID 39300217, 2024). "There exist a positive correlation between EZH2 and the five genes (CHEK1, MAD2L1, RFWD3, TRAIP, and TTK) in the majority of detailed cancer types as shown in the form of heatmap data." (PMID 34381492, 2021). "Fourteen genes that are essential to prevent EDR in cancer cells also are essential to prevent aneuploidy in mice [AURKA, BUB1B, BUB3, KIF11, MAD2L1, TPX2, TTK, SGOL1." (PMID 27144335, 2016). "In the end, the molecular function of Cdc20 in pan-cancer analysis indicated that BUB1, CCNA2, CCNB1, CDK1, MAD2L1, and PLK1 might play a critical role in its oncogenic function." (PMID 34527589, 2021). "Moreover, the pan-cancer analysis of the molecular function of Cdc20 indicated that BUB1, CCNA2, CCNB1, CDK1, MAD2L1, and PLK1 might play a critical role in interaction with Cdc20." (PMID 34527589, 2021). "In addition, CDC20, CDK4, MCM6, MAD2L1, MCM2 and MCM5 were leading genes intersecting in these four pathways, and a positive correlation between mRNA expression and LACTB was observed in most normal and cancer tissues." (PMID 33507917, 2021). "Thus, epithelial and non-epithelial human cancers are similar to Mad2l1-null HCC and T-ALL in having distinct karyotypes, perhaps because they experience different selective pressures." (PMID 28318489, 2017).
tumor (57 papers, 2007 to 2026). "In summary, our data demonstrate that TBX3 is overexpressed in a subset of human iCCA samples, and its high expression is associated with decreased MAD2L1 levels, decreased tumor cell proliferation, and prolonged survival." (PMID 38909034, 2024). "Our results indicated that MAD2L1 is associated with poor prognosis and tumor immune infiltration in patients with HCC." (PMID 36637946, 2023). "A significant positive association was also found between MAD2L1 levels and tumor immune cell infiltration, immune cell biomarkers, and immune checkpoint expression." (PMID 36637946, 2023). "It has been found that mutations in MAD2L1 promote tumor development by inducing chromosomal instability and aneuploidy." (PMID 36637946, 2023). "Our findings suggest that non-coding ribonucleic acids (ncRNAs)-mediated upregulation of MAD2L1 is associated with poor prognosis and tumor immune infiltration in HCC patients." (PMID 36637946, 2023). "In this study, we found for the first time that the MYC targeting gene MAD2L1 is associated with PCa bone metastasis tumor cell dormancy." (PMID 35305591, 2022). "The deletion of the MAD2L1 gene can cause chromosome instability and drive the development of tumours." (PMID 35037540, 2022). "High expression of MAD2L1 was linked with Edmondson-Steiner grading (P = 0.019) and tumor size (P = 0.042)." (PMID 35132379, 2022). "Further survival analyses, ROC curve analysis and representative image analysis, selected 5 hub genes, including CDK1, CDC20, CCNB1, CENPF, and MAD2L1, that were associated with early diagnosis, tumour stage, and poor outcomes of HCC." (PMID 34603487, 2021). "MAD2L1 is a key component of the mitotic spindle assembly checkpoint and associates with multiple tumor processes." (PMID 31419979, 2019). "Although mounting evidence suggests that high MAD2L1 or BUB1 are associated with tumor progression, study findings have been inconsistent." (PMID 26287798, 2015). "Six tumour-infiltrating immune cells (TICs) were found to be associated with MAD2L1 expression." (PMID 34838000, 2021). "Immunoinfiltration analysis further revealed that the high expression of MAD2L1 was associated with a significant increase in the level of immune cell infiltration, suggesting that MAD2L1 may be associated with a stronger anti-tumor immune response, which may improve patient prognosis." (PMID 40231267, 2025). "Given the existing in vivo evidence indicating that elevated glucose levels are associated with the upregulation of MAD2L1 expression in tumor tissues, it is crucial to determine whether this alteration occurs within the tumor cells or in the surrounding microenvironment." (PMID 40145796, 2025). "LZU‐WZLYCS01 is designed to achieve precise drug delivery through FGFR3 targeting while simultaneously leveraging A2‐mediated MAD2L1 inhibition to eradicate tumor cells, providing a promising therapeutic strategy to address these molecularly driven challenges." (PMID 41168906, 2026). "Immunohistochemistry (IHC) analysis revealed that A2 treatment decreased the expression of MAD2L1 and Ki‐67 in tumor tissues." (PMID 41168906, 2026).